TULP2 (TUB like protein 2)
Synonyms: CT65; TUBL2
Tractability: Antibody: UniProt places it where antibodies can reach, with medium confidence; its Gene Ontology location is reachable by antibodies, with medium confidence.
Gene: Protein-coding gene on chromosome 19 (48,880,965 to 48,898,744, reverse strand). Ensembl gene ENSG00000104804.
Subcellular location: Cytoplasm; Secreted
Subcellular location (Human Protein Atlas): Cytosol; Predicted to be secreted
Gene Ontology:
Molecular function: protein-containing complex binding
Biological process: protein localization to cilium; visual perception
Cellular component: cilium; cytoplasm; extracellular region
Genetic constraint (gnomAD): Loss-of-function variants: 69 observed, 65.19 expected, observed/expected ratio (o/e) 1.06, 90% interval 0.87 to 1.29. The upper end of that interval is the gene's LOEUF score, 1.29, which puts it in group 5 of 6, group 1 being the genes least tolerant of losing a copy. Missense variants: 652 observed, 694.25 expected, observed/expected ratio (o/e) 0.94, 90% interval 0.88 to 1. Synonymous variants: 267 observed, 280.07 expected, observed/expected ratio (o/e) 0.95, 90% interval 0.86 to 1.05.
Homologues: Orthologues: macaque TULP2 (90% identical), chimpanzee TULP2 (77% identical), pig TULP2 (62% identical), dog TULP2 (61% identical), rat Tulp2 (57% identical), mouse Tulp2 (56% identical), rabbit TULP2 (51% identical), zebrafish si:dkey-220f10.4 (33% identical), Drosophila melanogaster ktub (31% identical). Paralogues in human: TUB (36% identical), TULP1 (32% identical), TULP3 (32% identical), TULP4 (18% identical), WDR35 (13% identical).
Diseases named in the same sentence as TULP2 in open-access papers:
TULP2 is named in the same sentence as 10 diseases in open-access papers, as found by Europe PMC text mining. Sharing a sentence is not in itself a finding about the gene and the disease. The quoted sentences say what the papers report.
infertile (2 papers, 2021 to 2023). "To determine the cause of infertility in male Tulp2–/– mice, we examined the physiological parameters of sperm collected from cauda epididymis of the mice." (PMID 33763418, 2021).
male infertility (2 papers, 2021 to 2022). The inability of the male to effect fertilization of an ovum after a specified period of unprotected intercourse. "Both mouse lines of Tulp2 KO exhibited male infertility, abnormal tail morphology, and impaired sperm motility." (PMID 35619658, 2022). "Tulp2 KO mice were generated recently and exhibited male infertility due to abnormal sperm tail formation." (PMID 35619658, 2022). "Further analysis of TULP2 may provide a better understanding of the mechanism that regulates the sperm tail formation and may lead to better treatment for male infertility." (PMID 35619658, 2022). "TULP2 may play roles in the correct formation and/or maintenance of ODF, which may lead to abnormal tail morphology, impaired sperm motility, and male infertility." (PMID 35619658, 2022). "In summary, we reveal that mitochondrial sheath formation is not disrupted, but ODF structure is abnormal in Tulp2 KO mice, which may lead to impaired sperm motility and male infertility." (PMID 35619658, 2022).
Obesity (2 papers, 2018 to 2021). Accumulation of substantial excess body fat. "TULP2 is a member of the tubby gene family, and gene SNPs in the 19q13.33–13.43 chromosomal region are significantly related to severe obesity in French Caucasians." (PMID 34926636, 2021).
lung carcinoma (1 paper, 2019). "For lung cancer, it was shown that the methylation levels of HOXA9, KRTAP8-1, CCND1, and TULP2 have great potential for the early recognition of LUAD in the undetermined lung nodules." (PMID 31850197, 2019).
retinitis pigmentosa (1 paper, 2021). Retinitis pigmentosa (RP) is an inherited retinal dystrophy leading to progressive loss of the photoreceptors and retinal pigment epithelium and resulting in blindness usually after several decades. "Dysregulation of TULPs has been implicated in a number of human diseases including retinitis pigmentosa (TULP1 and TULP2), PKD (TULP3), and several cancers (TULP3)." (PMID 33187986, 2021).
teratozoospermia (1 paper, 2021). "The results confirmed that TULP2 is necessary for maintaining male fertility and Tulp2–/– mice showed the phenotype of oligo-astheno-teratozoospermia." (PMID 33763418, 2021).
cancer (3 papers, 2019 to 2021). A tumor composed of atypical neoplastic, often pleomorphic cells that invade other tissues. "Rs4801778-T (PLEKHA4), rs11919389-C (ZBTB11), rs13050728-C (IFNAR2), and rs10774671-A (OAS1) exhibited a positive or negative regulation in TULP2, HSD17B14, LOC285359, LOC100009676, SENP7, IFNAR2, OAS3, and OAS1 in multiple cancer types." (PMID 35082790, 2021).
tumor (1 paper, 2019). "The results further confirmed that the hypermethylation of HOXA9 and the hypomethylation of KRTAP8-1, CCND1, and TULP2 were observed in LUAD tumor samples." (PMID 31850197, 2019). "In this study, we systematically analyzed the DNA methylation data of LUAD and found that the hypermethylation of HOXA9 and the hypomethylation of KRTAP8-1, CCND1, and TULP2 were observed in LUAD tumor samples." (PMID 31850197, 2019). "In these LUAD patients, the methylation of HOXA9 was significantly upregulated, whereas the methylation of KRTAP8-1, CCND1, and TULP2 were downregulated obviously in tumor samples compared with adjacent tissues." (PMID 31850197, 2019).
TULP2 also shares sentences with these, for which no sentence is quoted: diabetes (1 paper); lung adenocarcinoma (1).